NOS3 (nitric oxide synthase 3)
Diseases named in the same sentence as NOS3 in open-access papers (continued):
Sharing a sentence is not in itself a finding about the gene and the disease.
Stroke (50 papers, 2011 to 2025). Sudden impairment of blood flow to a part of the brain due to occlusion or rupture of an artery to the brain. "Diabetic subjects often suffer impaired NOS3 activity and remain at the higher risk of stroke and poor outcomes." (PMID 36290774, 2022). "However, no studies have yet assessed the relationship between this or other NOS3 polymorphisms and cerebral collaterals in stroke." (PMID 39519182, 2024). "Finally, an analysis of the population-based, biracial Stroke Prevention in Young Women case-control study found two SNPs in the NOS3 gene associated with ischemic stroke in the black women but not in white women." (PMID 34828431, 2021). "Thus, we demonstrate that stroke-associated comorbidity accompanying NOS3 dysfunctions may depreciate the early phase benefits of RIC in thrombotic stroke, which needs to be carefully investigated in clinical trials." (PMID 36290774, 2022). "Some key genetic markers associated with stroke are brain-derived neurotrophic factor (BDNF), apolipoprotein E (ApoE, variant ε4), angiotensin-converting enzyme (ACE), and nitric oxide synthase 3 (NOS3)." (PMID 40142325, 2025). "The overactivation of NOS3 after stroke can produce nitric oxide (NO), which enhances the synthesis of proinflammatory mediators, participates in the formation of oxygen free radical damage, and causes brain edema with vascular smooth muscle relaxation." (PMID 35355727, 2022). "The genetic deletion of NOS3 augmented microvascular dysfunctions and brain tissue hypoxia in aged mice and also exacerbated acute stroke injury in young mice, establishing the critical role of endothelial NO in neurovascular protection." (PMID 36290774, 2022). "In all 192 anti-stroke plants, there are also many compounds which can interact with target NOS3, PDE5A, PSD-95." (PMID 28117389, 2017). "Most of candidate compounds and anti-stroke plants are tended to interact with target NOS3, PSD-95 and PDE5A." (PMID 28117389, 2017). "We observed significant associations with NOS3 variants and CHD and heart failure and significant pharmacogenetic effects for stroke and all cause mortality." (PMID 22470539, 2012). "Other genes associated with stroke and/or VaD risk include angiotensin-converting enzyme (ACE; only stroke), alpha-1 antichymotrypsin (ACT), glutamate-cysteine ligase modifier (GCLM), endothelial nitric oxide synthase (NOS3), and brain-derived neurotrophic factor (BDNF)." (PMID 39063013, 2024). "Thus, we demonstrated that NOS3 activation by RIC during stroke is an essentially required to enhance the CBF." (PMID 36290774, 2022). "In this preclinical trial of RIC and GRI therapies in murine models of stroke, we tested the hypothesis that reduced NOS3 would abolish the benefits of both therapies." (PMID 36290774, 2022). "In addition, the Akt1/Nos3 signaling pathway is thought to be highly beneficial to stroke outcome, weather by upregulation of Akt1 or by subsequent activation of Nos3." (PMID 32558293, 2020). "However, in these plants, the number of candidate anti-stroke compounds for each targets dramatically reaches a maximum of 134 (target NOS3) and a minimum of 62 (target SOD1)." (PMID 28117389, 2017). "Other SNPs in genes involved in inflammation (APOE and IL6), oxidative stress (NOS3 and SOD2), and As metabolism (AS3MT, CBS, GSTO1, and MTHFR) showed nominally significant interactions with well-water As for associations with CVD, CHD, or stroke." (PMID 25575156, 2015). "Thus, we conclude that preexisting NOS3 dysfunctions due to comorbidities may neutralize the benefits of RIC in stroke, which can be turned protective in combination with GRI." (PMID 36290774, 2022). "As anticipated, the partial depletion of NOS3 abolished the acute effect of the RIC therapy in enhancing CBF, as measured at 4 h post-stroke (p = 0.470)." (PMID 36290774, 2022).
Stroke (continued). "Importantly, GWAS have associated variants of several of the gene targets of miR-24-3p;FAF1, GATA3, MMP14, NOS3 and PTPRF with stroke." (PMID 36613546, 2022). "Conversely, five genes (CLCN6, OGDHL, COL6A3 [MIM: 120250], INSR [MIM: 147670], and NOS3 [MIM: 163729]) were found in the “long survivor” group but not in the “stroke” group." (PMID 32898326, 2020). "In hippocampal tissues, mRNA expression studies at 1 h and 24 h, and strongly elevated (Egr1, Akt1, Kras, Src, Foxo, Srf, Vegfr2, Nos3, Nos1) and decreased (Nos2, Nfkb) gene expression (Mapk1 not activated) also support BPC 157 beneficial effect on brain lesions, given in reperfusion in stroke-rats." (PMID 34203464, 2021).
type 2 diabetes (48 papers, 2005 to 2026). "In contrast to our study, in a Spanish population of CKD patients with type 2 diabetes, the NOS3 rs2070744's CC genotype was linked to advanced chronic kidney disease." (PMID 39246453, 2024). "Several genetic variants in the NOS3 locus are associated with the development of type 2 diabetes and susceptibility to other metabolic complications." (PMID 33374571, 2020). "The aim of this study was, therefore, to investigate the association of a genetic polymorphism of CNDP1-D18S880 and -rs2346061, NOS3-rs1799983, and MnSOD-rs4880 genes with the development of diabetic nephropathy among Malaysian type 2 diabetic patients." (PMID 30719346, 2019). "Since homozygous carriers of the NOS3 G894T variant are predicted to have decreased enzyme activity, the association between NOS3 genotype and type 2 diabetes, and possible effect modification by body mass index (BMI) were evaluated." (PMID 24278136, 2013). "Targeting Nos3, the gene encoding eNOS, or endothelial nitric oxide synthase was found to result in nephropathic changes in mouse models of type 1 and type 2 diabetes that mimic many aspects of human disease due to inhibition of nitric oxide formation." (PMID 22461787, 2012). "ESR1 XbaI and G894T NOS3 polymorphisms may be useful in accessing insulin resistance and type 2 diabetes risks, even before menopause and occurrence of metabolic disease." (PMID 25077953, 2014). "ESR1 XbaI and G894T NOS3 polymorphisms may be useful in accessing insulin resistance and type 2 diabetes risks in all women, even before menopause and occurrence of metabolic disease." (PMID 25077953, 2014). "Endothelial NO synthase (eNOS) activity is an important vascular modulator which is altered in diabetes, and functionally significant polymorphisms of the eNOS (NOS3) with lower production of NO are associated with the development of nephropathy in patients with type 1 and type 2 diabetes." (PMID 22900035, 2012). "Nitric oxide synthases (NOS1, NOS2, and NOS3) and myeloperoxidase (MPO), which have been implicated in the development of type 2 diabetes, are also important ROS-generating enzyme families." (PMID 36902173, 2023). "A total of 92 genes were intersected between DEGs and DMRs-targeted genes, of which Nos3, Pik3r1, Socs1, and Acly were gathered in type II diabetes mellitus, insulin resistance, and metabolic pathways." (PMID 37287451, 2023). "The intersected genes between DEG- and DMR-targeted genes were gathered in type II diabetes mellitus, insulin resistance, and metabolic pathways, which referred to Nos3, Pik3r1, Socs1, and Acly." (PMID 37287451, 2023). "For example, concomitant presence of CETP B1, NOS3 T and ANGPTL8 T alleles augments the risk of both CHD and type 2 diabetes." (PMID 32000781, 2020). "A previous study has shown that ESR1 and NOS3 predict postmenopausal CVD-related endothelial responses and can be used to predict insulin resistance and type 2 diabetes risk." (PMID 31752216, 2019). "Of note, in a type 2 diabetes mouse model, physical exercise-induced KLF2 expression was shown to activate endothelial nitric oxide synthase (eNOS/NOS3), resulting in improved vasodilation." (PMID 40076813, 2025).
metabolic syndrome (45 papers, 2008 to 2026). A cluster of metabolic risk factors for CARDIOVASCULAR DISEASES and TYPE 2 DIABETES MELLITUS. "This case-control study revealed that NOS3-c.894G>T transversion is associated with metabolic syndrome risk among Iranian-Azerbaijanis." (PMID 33995953, 2021). "Of note, polymorphism of the NOS3 gene (codes for endothelial NOS, eNOS), specifically the T-786C SNP, is associated with risk of metabolic syndrome in schizophrenia." (PMID 32982068, 2020). "The purpose of this study was to examine possible associations of the NOS3 T-786C polymorphism (rs2070744) with serum lipid levels on the basis of lifestyle factors for tailoring prevention of dyslipidemia." (PMID 23122449, 2012). "We investigated whether NOS3-c.894G>T transversion (rs1799983), which causes the substitution of glutamate with aspartate (E298D) in the oxygenase domain of endothelial nitric oxide synthase (eNOS), is associated with susceptibility to metabolic syndrome (MetS) risk in Iranian-Azerbaijanis." (PMID 33995953, 2021). "Recent studies also demonstrate that NOS3-knockout mice develop dyslipidemia, insulin resistance, decreased insulin-dependent glucose uptake in skeletal muscles and adipose tissue, and hypertension, mimicking the phenotype of MS." (PMID 22164159, 2011). "ApoE/NOS3−/− mice also inherited the dyslipidemia phenotype of ApoE−/− mice." (PMID 36360235, 2022). "In this study, we observed that NOS3 polymorphism does not have any association with stage of CKD, presence of metabolic syndrome, as well as the level of plasma NO." (PMID 39246453, 2024). "Therefore, it is not surprising to find that NO is depleted in NOS3-knockout mice and that these mice exhibited increased abdominal fat mass, dyslipidemia, and insulin resistance." (PMID 33816486, 2021). "Genetic variations in NOS3 gene (rs1799983 and rs2070744) were not correlated with stage of CKD, metabolic syndrome, and plasma NO level." (PMID 39246453, 2024).
myocardial infarction (44 papers, 2008 to 2025). Gross necrosis of the myocardium, as a result of interruption of the blood supply to the area, as in coronary thrombosis. "The function of miR‐134 in myocardial infarction is to accelerate myocardial hypoxia/reoxygenation injury by targeting nitric oxide synthase 3, encoding endothelial nitric oxide synthase, which generates nitric oxide and plays a protective role in the cardiovascular system." (PMID 32783377, 2020). "Recently we demonstrated that depletion of circulating NOS3 increases the size of reperfused myocardial infarction in a murine model." (PMID 25875863, 2015). "Circulating NOS3 ameliorates maladaptive left ventricular remodeling following reperfused myocardial infarction." (PMID 25875863, 2015). "It is the aim of the present study to evaluate the effects of depletion of circulating NOS3 on adverse LV functional and structural remodeling after reperfused myocardial infarction." (PMID 25875863, 2015). "The findings of the present study show that blood-borne NOS3 attenuates adverse left ventricular remodeling in reperfused myocardial infarction." (PMID 25875863, 2015). "In conclusion, circulating NOS3 attenuates maladaption in the healing process of reperfused myocardial infarction through preserved LV dimension and function accompanied by altered scar formation." (PMID 25875863, 2015). "A widely explored polymorphism of the eNOS gene, the G894T (rs1799983) polymorphism encoded by the NOS3 gene in chromosome 7, has been linked to increased risk of coronary artery disease (CAD), myocardial infarction, coronary spasms, hypertension, and ischemic stroke." (PMID 26561052, 2015). "Furthermore, depletion of circulating NOS3 was associated with significantly increased end-systolic (ESV) and end-diastolic volume (EDV) 3 weeks post myocardial infarction." (PMID 25875863, 2015). "Thus, circulating NOS3 limits adverse remodeling following myocardial infarction likely through increased NO bioavailability during reperfusion after myocardial infarction." (PMID 25875863, 2015). "Our findings suggest that modulating circulating NOS3 might be a promising therapeutic approach in attenuating LV adverse remodeling following myocardial infarction." (PMID 25875863, 2015). "We hypothesized that the circulating blood born NOS3 also modulates the severity of myocardial infarction in disease models." (PMID 24346018, 2014). "We have shown that NO protects against myocardial ischemia/reperfusion (I/R) injury and that depletion of circulating NOS3 increases within 24h of ischemia/reperfusion the size of myocardial infarction (MI) in chimeric mice devoid of circulating NOS3." (PMID 25875863, 2015).
preeclampsia (43 papers, 2009 to 2025). Preeclampsia is a hypertensive disorder of pregnancy that is characterized by new-onset hypertension with proteinuria presenting after 20 weeks of gestation, and depending on mild or severe forms may initially present with severe headache, visual disturbances, and hyperreflexia. "The NOS3 G894T genetic polymorphism was also associated with preeclampsia susceptibility in pregnant Turkish patients." (PMID 40142738, 2025). "The evidence that NOS3 G894T and T-786C polymorphisms increase the risk of preeclampsia is biologically plausible." (PMID 26997284, 2016). "Our data support that the NOS3 T-786C SNP is associated with preeclampsia and the severity of its complications." (PMID 26317342, 2015). "The most significant clinical risk factor was previous preeclampsia, while amongst genetic risk factors, only SNPs in the NOS3 gene were associated with preeclampsia." (PMID 26317342, 2015). "Subsequent multivariate analysis showed that only NOS3 T-786C was associated with preeclampsia independently from age, height, or weight." (PMID 26317342, 2015). "Our data also agree with NOS3 polymorphism being associated with more severe forms of preeclampsia, and in the present study, this SNP was particularly associated with the most severe complications (HELLP syndrome and eclampsia)." (PMID 26317342, 2015). "In this project we aimed to replicate previous findings on the association between the three most commonly investigated NOS3 polymorphisms (4b/a, T-786C and G894T) and preeclampsia, in a GAS conducted on a homogeneous population of Caucasian origin (Greeks)." (PMID 22051068, 2011). "We examined the association of three common variants of the NOS3 gene (4b/a, T-786C and G894T) and their haplotypes in a case-control sample of 102 patients with preeclampsia and 176 women with a history of uncomplicated pregnancies." (PMID 22051068, 2011). "Genotyping for the NOS3 variants was performed and odds ratios and 95% confidence intervals were obtained to evaluate the association between NOS3 polymorphisms and preeclampsia." (PMID 22051068, 2011). "This study evaluated relations between common genetic variants and haplotypes in the NOS3 gene with preeclampsia." (PMID 22051068, 2011). "Therefore, the association of the NOS3 polymorphism with preeclampsia and the occurrence of HELLP and eclampsia indicate an important role of NO in the pathophysiology of this disease." (PMID 26317342, 2015). "We analyzed whether the NOS3 T-786C polymorphism was associated with more severe preeclampsia among the cases." (PMID 26317342, 2015). "In multivariate analysis, the only SNP that remained statistically significant for the risk of preeclampsia after correction for age, height and weight, and that was independent from other polymorphisms, was NOS3 T-786C, with an OR 3.56 (95% CI: 1:23 to 10:31)." (PMID 26317342, 2015). "However, preeclampsia is a complex disease with multifactorial etiology and therefore, a minor contributory pathogenetic role of NOS3 variants in conjunction with other genetic or environmental factors cannot be excluded." (PMID 22051068, 2011). "Thus, the available evidence from candidate-gene approach cannot support a major contributory role of NOS3 variants in preeclampsia pathogenesis." (PMID 22051068, 2011). "In summary, our data support that NOS3 T-786C polymorphism is the most important and independent genetic factor in this study associated with the occurrence of preeclampsia in a Brazilian population, and may predispose patients to more severe complications, such as HELLP syndrome and eclampsia." (PMID 26317342, 2015). "For example, the C allele of the NOS3 locus — a polymorphism 786T>C (rs2070744) — results in a decrease in eNOS expression and, thus, in a decrease in NO production, which in turn may be accompanied by an increased risk of hypertension, preeclampsia, diabetic nephropathy, and migraine." (PMID 41426971, 2025).